HIF1A (hypoxia inducible factor 1 subunit alpha)
Diseases named in the same sentence as HIF1A in open-access papers (continued):
Sharing a sentence is not in itself a finding about the gene and the disease.
glioma (continued). "Our study aligns with these findings, showing that PAX6 overexpression suppressed the expression of the HIF-1α gene and protein in glioma cells, whereas concurrent overexpression of PAX6 and HIF-1α mitigated the ferroptosis impact generated by PAX6." (PMID 41154694, 2025). "In glioma tissues and cells, SUMOization of IGF2BP2 promotes HIF1α expression, which in turn leads to cancer cell invasion and angiogenesis." (PMID 40469197, 2025). "The authors examined how hypoxia-induced stabilization of HIF-1α affects the expression of GOT1 and GOT2 in G55 human glioma cells, which possess the VHL protein and lack constitutive HIF-1α activation." (PMID 39914740, 2025). "Our findings enhance the understanding of glioma pathogenesis and the role of PAX6, while also providing an experimental foundation for further investigating the PAX6/HIF-1α axis." (PMID 41154694, 2025). "Seeking to understand the underlying mechanism, we considered prior studies identifying HIF1A as a direct client of HSP9025, and noting that HIF1A was reported to bind the ETS1 promoter in glioma cells." (PMID 40777467, 2025). "HIF-1α appears to bind to the promoter of CD133 (a marker gene of CSCs), promoting the production of CD133 +glioma stem-like cells through OCT4 and SOX2." (PMID 38716541, 2024). "Hence, VEGF expression in gliomas could be regulated both through HIF-1α and COX-2 pathways." (PMID 39055895, 2024). "Only HIF1A and STAT3 robustly showed significant positive correlations with METTL8 in all three glioma cohorts." (PMID 38744809, 2024). "In the glioma LN229 cell line, knockdown of HIF-1α inhibited cell invasiveness and increased therapeutic sensitivity by negatively modulating the time-dependent expression of miR-224-3p in hypoxia." (PMID 37588219, 2024). "For example, HIF1α is involved in promoting radioresistance by modulating AMPK-mediated ATM expression, promoting glioma invasion and stem cell formation via regulating MIR210HG and OCT1, and activating Ror1 transcription to influence cancer progression." (PMID 38893207, 2024). "Targeted intervention on the HIF-1α/LAMC1 signaling attenuates cell growth and invasion, suggesting a new strategy for glioma treatment." (PMID 38678297, 2024). "MCT1 and NHE1 expression is higher at the leading edge of tumors in GBM patients and in a rat glioma model; in contrast, MCT4 is upregulated in the perinecrotic tumor center, along with HIF1α, LDH, and CA9." (PMID 38786726, 2024). "In glioma, hypoxia upregulates SLC7A11 via the PI3K/AKT/HIF-1α axis to enhance glioma resistance to salazosulfapyridine-induced ferroptosis." (PMID 38304870, 2024). "The association of PDT with endostar, a recombinant human endostatin, led to prolonged survival of U251 glioma mice, significantly reducing the expression of both VEGF-A and HIF-1α." (PMID 39201395, 2024). "To explore the role of HIF-1α in glioma development, we first examined the mRNA expression of HIF-1α in glioma tissues and glioma cells." (PMID 38734702, 2024). "For example, HIF1α was found to orchestrate regeneration resistance by upregulating AMPK-mediated ATM expression in severe hypoxia, while it promotes glioma invasion and stem cell formation by regulating MIR210HG and OCT1." (PMID 38893207, 2024). "TGF-β is secreted by gliomas, and its expression increases under hypoxia due to the activity of NANOG, a transcription factor induced by HIF-1α, which promotes the stemness signature of GSCs." (PMID 38794149, 2024). "Beyond VEGFA, IGF2BP2 can also indirectly regulate hypoxia-inducible factor 1 subunit alpha (HIF1A) and matrix metalloproteinase 14 (MMP14) to drive vasculogenic mimicry in glioma." (PMID 39596216, 2024). "Specifically, CD44 was found in a perinecrotic, hypoxic niche with HIF-1α- and HIF-2α-positive glioma cells, as well as a perivascular, highly oxygenated niche with pseudo-hypoxic, HIF-2α-positive, stem-like cells." (PMID 39333557, 2024).
glioma (continued). "The expression of FBXO22, VHL, HIF-1α, and VEGFA was detected by IHC staining using anti-FBXO22, VHL, HIF-1α, and VEGFA antibodies in the tissue sections of glioma patients." (PMID 38519492, 2024). "For instance, in a glioma stem cell study, the CLOCK/BMAL1 complex within these cells was found to stimulate tumor angiogenesis within the glioma TME by modulating HIF1α through the transcriptional regulation of OLFML3." (PMID 38607733, 2024). "Decreased HIF-1α and VEGF expression of glioma cells in a dose- and time-dependent manner under normoxic and hypoxic conditions." (PMID 39055895, 2024). "HIF1α/HIF2α induce the dedifferentiation of glioma cells into CSCs through SOX2 under hypoxic conditions, thereby promoting chemoresistance of glioma cells." (PMID 37576862, 2023). "In case of SIRT3 (p = 0.0142) and HIF1α (p = 0.0385) significant upregulation was observed while non-significant upregulated expression was observed in PARP1 (p = 0.203) in glioma samples as compared to healthy samples." (PMID 36809279, 2023). "In glioma C6 cells, the activation of ERK/Akt, the pro-angiogenic proteins were blocked by biochanin-A, and also VEGF and HIF-1α (hypoxia-inducible factor 1 alpha) were inhibited (Jain, Lai and Bhushan, 2015)." (PMID 38106650, 2023). "In glioma, it has been already reported that TMZ-responsive cells positively modulate CMA-related genes and abrogate HIF-1α expression and activity after treatment with this drug." (PMID 37407979, 2023). "In glioma, hypoxia augments tumor resistance to Sulfasalazine-induced ferroptosis by increasing SLC7A11 expression through activation of the PI3K/AKT/HIF-1α pathway." (PMID 37978473, 2023). "Seven ferroptosis-related hub genes, namely SLC39A14, WWTR1, STEAP3, NOTCH2, IREB2, HIF1A, and FANCD2, were identified, all of which were highly expressed in glioma." (PMID 37978473, 2023). "The study showed that persistent oncogenic stress activated the AMPK–CREB1 pathway and regulated the transcription levels of HIF1α and GABPA to support glioma bioenergetics." (PMID 36715873, 2023). "We also performed IHC staining, utilizing PDGFRA antibody (OPC-like marker), EGFR antibody (AC-like marker) and HIF-1A antibody (MES-like marker) and confirmed the specific cell states are enriched in distinctive proteomic subsets of gliomas." (PMID 36720864, 2023). "Reduced HIF-1α levels in IDH mutant gliomas reflect epigenetic silencing of glycolytic switch–related genes; on the contrary, IDH wt gliomas show a glycolytic phenotype." (PMID 36831383, 2023). "Studies showed that PLOD2 was mediated by HIF-1α, TGF-β, and microRNA-26a/b to promote the occurrence and development of gliomas." (PMID 35479581, 2022). "The expression of p75NTR induces the stability of hypoxic factors HIF-1α and HIF-2α, which increases the migration, invasion, and stemness of glioma." (PMID 35956937, 2022). "In conclusion, we demonstrated that glioma resistance to SAS-induced ferroptosis was enhanced by hypoxia, owing to the activation of the PI3K/AKT/HIF-1α pathway and promotion SLC7A11 expression." (PMID 36439690, 2022). "Histological measurements revealed higher expression of HIF1a, GLUT3, and HK2 in labels in category W than in category M, which corresponded with the comparison between IDH wild-type and mutant gliomas based on pathological diagnoses." (PMID 35058510, 2022). "Research illustrates that lncRNA PCED1B-AS1 can up-regulate hypoxia-inducible factor 1-alpha (HIF-1α) expression, thus promoting cell proliferation, glucose uptake, and lactic acid release in glioma cells." (PMID 36353102, 2022). "In the study of glioma, PLOD2 is induced by hypoxia-inducible factor-1α (HIF-1α) and then activates the PI3K/AKT signaling pathway, which eventually leads to the occurrence of EMT." (PMID 35912206, 2022). "The analysis of the CGGA glioma genome database revealed a positive correlation between expression of PRMT3 and HIF1A in both primary and recurrent gliomas." (PMID 36351894, 2022).
glioma (continued). "The pathway leading to apoptosis involves the reduction of HIF-1α and its target genes (PGK-1 and VEGF) expression, suggesting that HIF pathway inhibition drives ACF-mediated glioma cell death." (PMID 35409080, 2022). "By using Chinese Glioma Genome Atlas (CGGA) gene correlation analysis, it was discovered the significant positive correlation between Sept9 and Hif-1α." (PMID 35096204, 2022). "HIF1α and HIF2α were successfully knocked out in CD133-CD15- primary glioma cells, and the same result was found for CD133-CD15- GL261 cells (data not shown)." (PMID 34976166, 2022). "HIF-1α binds to the CD133 promoter and promotes the production of CD133+ glioma, colon, and pancreatic CSCs via OCT4 and SOX2." (PMID 36014432, 2022). "In human glioma patient tissues, the expression of the RUNX1T1 gene and protein is downregulated, while the expression of HIF-1α is higher than that in normal brain tissues." (PMID 36231060, 2022). "Regulation of ECM stiffness and glioma cell migration by LOX expression have been shown in drosophila and mouse models, and LOX activity was reduced by HIF-1α knockdown." (PMID 36076905, 2022). "In glioma, RUNX1T1 has been viewed as a potential biomarker and possible target due to its interaction with Hypoxia-inducible factor 1α (HIF1α), which is closely related to the proliferation, survival, self-renewal, and invasiveness of glioma stem cells." (PMID 35902872, 2022). "In contrast, p75NTR gene knockdown stimulates the expression of HIF-1α, fibronectin, and L1CAM, and the phosphorylation of Src, focal adhesion kinase (FAK), and paxillin, which increase the migration of C6 glioma cells." (PMID 35956937, 2022). "Treatment of tumor-bearing mice with baicalein suppressed HIF1α, VEGF, and VEGFR2, indicating that baicalein suppressed the HIF1α/VEGF cascade in U87 gliomas." (PMID 35955525, 2022). "We collected tumor tissues, and the results demonstrated that HIF1α, HIF2α, CD133 and CD15 were highly expressed in these glioma tissues." (PMID 34976166, 2022). "Another novel small molecule, 103D5R, decreases HIF-1α expression, inhibits the transcription of HIF-1α target genes and prevents angiogenesis and metabolic adaptation in gliomas." (PMID 35409080, 2022). "Higher levels of PRDM1 were observed in high-HIF1A-expression GBM and lower-grade glioma, while higher levels of NFAT and IL10 were only observed in lower-grade glioma." (PMID 34305618, 2021). "HIF-1α is one of the key factors that regulates the expression of VEGF, which plays an important role in angiogenesis in gliomas." (PMID 34070746, 2021). "Conversely, the degradation of HIF-1α by oroxylin A or the inhibition of Hh/GLI1 signaling by cyclopamine led to the downregulation of the HIF-1α/Hh pathway and the increased expression of SUFU, thus restoring glioma cells’ chemosensitivity to TMZ." (PMID 34638233, 2021). "ELTD1 promotes glioma proliferation, migration and invasion by stimulating JAK/STAT3/HIF‐1α signalling pathway." (PMID 34755451, 2021). "Intriguingly, suppressing P2 × 7R with an antagonist or shRNA promotes cell growth through the up-regulation of EGFR, p-EGFR, HIF-1α, and VEGF in glioma cells." (PMID 34149360, 2021). "The expression levels of PDL1 (CD274), FOXO1, and PRDM1 in the high-HIF1A-expression group were significantly higher in both glioblastoma (GBM) and lower-grade glioma." (PMID 34305618, 2021). "Therefore, we first tested whether HIF‐1α regulated the expression of HAX1 in glioma." (PMID 34755451, 2021). "In glioma, lncRNA‐AHIF is the natural antisense transcript of hypoxia‐inducible factor‐1α (HIF‐1α) and is exactly complementary to the 3'‐untranslated region of HIF‐1α mRNA." (PMID 33586248, 2021). "Numerous signaling pathways have been implicated in VEGFA-induced endothelial cell proliferation, typically AKT and ERK, which activate glioma cells and indirectly activate VEGFA through their action on HIF-1α 31,32." (PMID 34539892, 2021).
glioma (continued). "To verify hypoxic conditions in growth tumors, we analyzed the amount of HIF1α and GAPDH mRNA in glioma cells 21 days after their injection." (PMID 33546324, 2021). "We found that the levels of exhausted T cell and B cell were higher in high-HIF1A-expression tumors in both GBM and lower-grade glioma groups." (PMID 34305618, 2021). "The hypoxic inducible factor 1A (HIF1A) pathway has been known to play an important role in tumor progression in various cancers, including lower-grade (Grade II/III) gliomas (LGGs)." (PMID 34439934, 2021). "Co-expression of HIF-1α, which plays a critical role in GBMs progression, and CXCR4 was observed in hypoxic regions of tumor, i.e., pseudopalisading glioma cells." (PMID 34200145, 2021). "Regarding the dynamic effects of HIF1A and OR7E156P on tumor growth, a subcutaneously implanted tumor model was constructed in nude mice by injecting glioma cells transduced with Adv-HIF1A (Adv-NC as control) and/or Lsh1-OR7E156P (Lsh-NC as control)." (PMID 34422645, 2021). "In summary, OR7E156P/miR-143 axis regulates HIF-1α downstream ZEB1, and VEGF signaling pathways, affecting glioma cell invasion." (PMID 34422645, 2021). "First, we compared the expression levels of HIF1A between primary GBM (IDH wild-type) and lower-grade glioma." (PMID 34305618, 2021). "Second, TTF application decreases the levels of VEGF, HIF1α, MMP‐2 and MMP‐9 via the suppression of NF‐κB, thus suppressing glioma angiogenesis." (PMID 33300633, 2021). "This study demonstrated that canstatin overexpression can inhibit glioma growth and VM-like structure formation, which is correlated with reduced expression of VEGF and HIF-1α." (PMID 34434564, 2021). "CCK-8 assays, cell transwell assays, and three-dimensional cell culture methods were used for evaluating the function of IGF2BP2, OIP5-AS1, miR-495-3p, HIF1A and MMP14 in biological behaviors of glioma cells." (PMID 34345216, 2021). "Our study revealed that hypoxia-dependent miR-210-3p induction is transcriptionally upregulated by HIF-1α and that it positively increased TGF-β expression of in glioma cells." (PMID 34197482, 2021). "A previous study showed that inhibition of fatty acid synthase (FASN) blocks HIF-1α/VEGF-A signaling in response to hypoxia, and suppresses neovascularization in glioma by upregulating VEGF165b37." (PMID 33446752, 2021). "IGF2BP2 enhances the stability of OIP5-AS1, thereby increasing the binding of OIP5-AS1 to miR-495-3p, weakening the binding of miR-495-3p to the 3'UTR of HIF1A and MMP14 mRNA, and ultimately promoting the formation of VM in glioma." (PMID 34345216, 2021). "Hypoxia (1% O2) significantly induced HIF1A protein levels, especially in U251-MG and U87-MG cells; the expression of OR7E156P showed to be dramatically upregulated within glioma cells than that within HEB cells, more upregulated in U251-MG and U87-MG cells." (PMID 34422645, 2021). "Another recent study revealed that exosomes derived from hypoxic glioma stem cells contain an elevated level of Linc01060, which supports glioma progression by regulating the MZF1/c-Myc/HIF-1α axis and is correlated with a poor clinical prognosis." (PMID 34681857, 2021). "In a subcutaneous murine glioma model, the tumor hypoxic fraction resists a high single dose of radiation therapy by activating the PERK/eIF2α/GADD34c axis, when HIF-1α is rather involved in post-irradiation re-progression." (PMID 34539584, 2021). "In that context, hypoxia induced increased expression of HIF-1α and HIF-2α has been noted in neuroblastoma and glioma CSCs." (PMID 34099013, 2021). "Vice versa, hypoxic and glycolytic markers like HIF-1α, CAIX, GLUT1, and MCT1 are upregulated in glioma cells under bevacizumab treatment." (PMID 34073734, 2021). "All these considerations contributed to elect HIF-1α not only as an early biomarker of responsiveness to TMZ, but also as a biomarker of CMA switch on/off in glioma, being crucial for glioma cell responsiveness to TMZ treatment." (PMID 33672324, 2021).
glioma (continued). "In gliomas, lactate also triggers HIF-1α activation in a hypoxia-independent manner by inhibition of HIF-1α proline hydroxylation." (PMID 34070746, 2021). "Secondly, a human fetal glial cell line SVG p12 and four glioma cell lines, U87-MG, T98-G, U251-MG, and LN229, were exposed to 1% or 20% oxygen saturations, HIF1A protein levels and OR7E156P expression levels were subsequently determined." (PMID 34422645, 2021). "Overall, our results demonstrated that positive correlation between PD-L1 and HIF-1α in glioma, and provide an alternative strategy, inhibiting HIF-1α, as combination therapies with immunotherapies to advance glioma treatment." (PMID 34118979, 2021). "Accordingly, HIF-1α target genes, including many glycolytic genes, are downregulated in IDH mutant compared to IDH wt gliomas." (PMID 34073734, 2021). "miR-566 downregulates VHL expression and upregulates HIF-1α and VEGF expression to promote angiogenesis in glioma cells." (PMID 32993787, 2020). "Echinomycin, which blocks the binding of HIF-1α, repressed CDCA2 expression in glioma U251 cells (GSE7835)." (PMID 32509575, 2020). "Induction of HIF-1α and its target BNIP3 was also detectable in LNT-229 glioma cells as well as in LIM1215 and SW948 cells in the presence of cetuximab and bevacizumab in hypoxia." (PMID 33092032, 2020). "Next, we knocked down HIF1A and determined the expression levels of PDIA3P1 and miR-124-3p in glioma cells." (PMID 32127518, 2020). "While greater focus has been given to HIF-1a, recent findings have indicated that HIF-2a is preferentially expressed in glioma cancer stem cells and correlates negatively with patient survival in clinical glioblastoma." (PMID 32566921, 2020). "The results showed that inhibition of HIF-1α expression in glioma cells with overexpression of NKILA can effectively reverse the stimulation of the Warburg effect and angiogenesis in gliomas." (PMID 32382013, 2020). "In glioma, the targeted inhibitory effect of increasing miR-23b on VHL unsurprisingly activates HIF-1α/VEGF signaling to promote tumor progression." (PMID 32014012, 2020). "Previously, we have documented upregulation of FAT1 gene in glioblastoma (GBM) tumors which was found to increase the expression of proinflammatory markers, HIF-1α, stemness genes and EMT markers in glioma cells." (PMID 31992226, 2020). "RNAseq analysis also indicated regulation of several pathways related to HIF-1α and VEGF such as NF-kappaB, PDGFb and Ang/Tie2 signaling for RNAseq of brain microvessels from experimental stroke and glioma models." (PMID 32529267, 2020). "A total of 18 genes were significantly negatively correlated with DGCR5, including GNAI3, VIM, ITGB1, HIF1A, and HDAC1, all of which are critical factors affecting glioma development." (PMID 33085646, 2020). "In this machinery, low oxygen states induce glioma stem cells to release signaling mediators, such as VEGF, PDGF, and HIF-1α." (PMID 32456359, 2020). "Then, we knocked down ELTD1 with short hairpin RNAs in U-87MG and U-138MG glioma cells and found that the protein levels of p-JAK, p-STAT3, HIF-1α, and Frataxin notably decreased compared with the levels in the control group." (PMID 31554859, 2019). "First, we measured the expression levels of HIF-1α and ELTD1 in 61 glioma samples using RT-PCR to identify the correlation between ELTD1 and HIF-1α." (PMID 31554859, 2019). "In several glioma cell models, CA9 strongly co-localized with HIF-1α, indicating its induction in hypoxic regions of this tumor type." (PMID 31414377, 2019). "(K) Immunoblot with antibodies against HIF1α, Glut1, and VEGFA from protein lysates derived from CRISPR-IUE glioma overexpressing Daam2 or control." (PMID 29053101, 2017). "Therefore, we investigated whether HIF-1α could regulate PLOD2 expression in glioma cells." (PMID 28410212, 2017). "Consistently, the immunohistochemistry analysis of 45 glioma tissues also showed a positive correlation between PLOD2 and HIF-1α." (PMID 28410212, 2017).